ANKRD22 (ankyrin repeat domain 22)
Synonyms: MGC22805
Tractability: No criterion of Open Targets' tractability assessment is met for any kind of drug.
Gene: Protein-coding gene on chromosome 10 (88,819,896 to 88,851,844, reverse strand). Ensembl gene ENSG00000152766.
Subcellular location (Human Protein Atlas): Nucleoplasm
Gene Ontology:
Biological process: immune response; leukocyte migration; response to wounding
Genetic constraint (gnomAD): Loss-of-function variants: 22 observed, 20.74 expected, observed/expected ratio (o/e) 1.06, 90% interval 0.76 to 1.51. The upper end of that interval is the gene's LOEUF score, 1.51, which puts it in group 6 of 6, group 1 being the genes least tolerant of losing a copy. Missense variants: 188 observed, 209.29 expected, observed/expected ratio (o/e) 0.9, 90% interval 0.8 to 1.01. Synonymous variants: 75 observed, 80.32 expected, observed/expected ratio (o/e) 0.93, 90% interval 0.77 to 1.13.
Homologues: Orthologues: chimpanzee ANKRD22 (97% identical), macaque ANKRD22 (95% identical), pig ANKRD22 (92% identical), rabbit ANKRD22 (91% identical), guinea pig ANKRD22 (87% identical), mouse Ankrd22 (86% identical), rat Ankrd22 (85% identical), dog ANKRD22 (84% identical), tropical clawed frog ankrd22 (63% identical), zebrafish ankrd22 (52% identical), Drosophila melanogaster iPLA2-VIA (21% identical), Caenorhabditis elegans ipla-7 (13% identical), and 2 more. Paralogues in human: PLA2G6 (29% identical), TONSL (21% identical), NFKBIB (17% identical), NFKBIA (14% identical).
Diseases named in the same sentence as ANKRD22 in open-access papers:
ANKRD22 is named in the same sentence as 33 diseases in open-access papers, as found by Europe PMC text mining. Sharing a sentence is not in itself a finding about the gene and the disease. The quoted sentences say what the papers report.
pancreatic cancer (10 papers, 2019 to 2025). "In this study, we used TCGA and GEO datasets to construct 5-mRNA signature (ANKRD22, ARNTL2, DSG3, KRT7, PRSS3) that is associated with the prognosis of pancreatic cancer patients." (PMID 36906533, 2023). "Several studies suggest that the expression level of ANKRD22 is related to prognosis of pancreatic cancer, endometrial carcinoma, hepatocellular carcinoma." (PMID 36906533, 2023). "There are few studies on ankyrin repeat domain 22 (ANKRD22) and related studies in medicine that have shown that the expression levels of ANKRD22 in human breast cancer and pancreatic cancer tissues are significantly higher than those in normal breast tissues." (PMID 34946891, 2021). "In particular, ANKRD22 has been previously diagnosed as a marker for pancreatic cancer, pancreatic ductal cancer, and NSCLC." (PMID 32651974, 2021). "In particular, ANKRD22 has been reported to be a marker of pancreatic cancer." (PMID 32651974, 2021). "The role of ANKRD22 in pancreatic cancer progression requires further study." (PMID 31612115, 2019). "High expression of EPYC, ANKRD22, ARNTL2, DSG3, KRT7, PRSS3 and MET predict poor prognosis of pancreatic cancer patients." (PMID 38184732, 2024). "A machine learning based-study reported that the 5-gene signature including ANKRD22, ARNTL2, DSG3, KRT7, PRSS3 performed well on both our chosen training dataset and validation dataset and provided a new way to predict the prognosis of pancreatic cancer patients." (PMID 38184732, 2024).
colorectal cancer (8 papers, 2020 to 2025). A primary or metastatic malignant neoplasm that affects the colon or rectum. "ANKRD22, a nuclear-encoded mitochondrial protein, can be involved in gastric mucosal injury and various cancer processes, such as colorectal cancer and prostate cancer." (PMID 38102696, 2023). "Another nucleus-encoded mitochondrial membrane protein ANKRD22 (Ankyrin Repeat Domain 22) was shown to be activated by the tumour microenvironment and upregulated in colorectal cancer-initiating cells." (PMID 34769108, 2021). "For instance, in colorectal cancer, ANKRD22 extensively contributed to metabolic reprogramming, leading to colorectal cancer growth." (PMID 40225855, 2025). "In this study, we identified a novel protein, ANKRD22, which was induced by the TME through activation of p38/MAX pathway and associated with the reprogramming of colorectal cancer cells." (PMID 31903135, 2020). "In colorectal cancer cells, ANKRD22 plays a role in promoting glycolysis and reducing ATP levels." (PMID 36906533, 2023). "ANKRD22 is a functionally unknown protein, but it was recently reported to be overexpressed in malignant cancers such as non-small cell lung cancer, colorectal cancer, and breast cancer." (PMID 34584137, 2021).
breast carcinoma (6 papers, 2020 to 2023). "Therefore, our results indicated that the expression level of ANKRD22 was upregulated in breast cancer tissue and associated with the prognosis and clinical-pathological features." (PMID 32651974, 2021). "The present study initially explored the possible involvement of ANKRD22 in the progression and development of breast cancer through analyzing ANKRD22 mRNA expression levels in 70 clinical samples." (PMID 32651974, 2021). "Our study demonstrated that ANKRD22 was dramatically upregulated in both breast cancer tissues and cell lines." (PMID 32651974, 2021). "qRT-PCR assay confirmed the positive correlation between the expression levels of NUSAP1 and ANKRD22 in breast cancer tissues from 53 patients." (PMID 32651974, 2021). "Hence, ANKRD22 may be a valuable diagnostic marker for breast cancer." (PMID 32651974, 2021). "To explore the potential effects of ANKRD22 on the progression and development of breast cancer, we analyzed ANKRD22 mRNA expression levels in 70 clinical samples, including 53 breast cancer tissue samples and 17 normal breast tissue samples." (PMID 32651974, 2021). "Results from IHC assay showed that the expression of ANKRD22 in human breast cancer tissues was higher than that in normal tissues." (PMID 32651974, 2021). "In breast cancer tissues, ANKRD22 promoted breast cancer cell malignancy by activating the Wnt/β-catenin pathway by regulating nucleolar and spindle-associated protein 1 (NuSAP1) expression." (PMID 34584137, 2021). "In this study, we demonstrated that the expression level of ANKRD22 in breast cancer tissue was significantly higher than that in normal breast tissue." (PMID 32651974, 2021). "Further understanding of the molecular mechanisms of ANKRD22 in the onset and progression of breast cancer is particularly important for developing new strategies for treating patients with metastatic and recurrent breast cancer." (PMID 32651974, 2021). "Using immunohistochemistry, we demonstrated that the expression level of ANKRD22 in human breast cancer tissues was significantly higher than that in normal breast tissues." (PMID 32651974, 2021). "This study aimed to assess the role of ankyrin repeat domain 22 (ANKRD22) in the progression of breast cancer and investigate the molecular mechanism." (PMID 32651974, 2021). "The results showed that breast cancer tissues displayed significantly higher expression levels of ANKRD22 than normal breast tissue (p < 0.01)." (PMID 32651974, 2021). "ANKRD22 knockdown suppressed the proliferation, invasion, and EMT of breast cancer cells and the underlying mechanism was through regulating NuSAP1." (PMID 32651974, 2021). "The NUSAP1 overexpression vector and ANKRD22 shRNA plasmids were co-transfected into breast cancer cells." (PMID 32651974, 2021). "The level of ANKRD22 expression in breast cancer tissue was higher than that in normal breast tissue." (PMID 32651974, 2021). "The expression of ANKRD22 in four different breast cancer cell lines was also measured." (PMID 32651974, 2021). "The results from the current study showed that ANKRD22 contributed to breast cancer progression, indicating that it might act as a potential marker for the therapy of breast cancer." (PMID 32651974, 2021). "Moreover, breast cancer patients with higher ANKRD22 expression had lower survival rates compared to those with lower ANKRD22 expression." (PMID 32651974, 2021). "In view of the potentially important role of NuSAP1 in the development of breast cancer, along with the predicted relationship between NuSAP1 and ANKRD22 from the Cancer Genome Atlas (TCGA) database, it may be possible that ANKRD22 affects the development of breast cancer via NuSAP1." (PMID 32651974, 2021). "In summary, this study demonstrated that ANKRD22 enhanced breast cancer cell malignancy by activating the Wnt/β-catenin pathway via modulating NuSAP1 expression, which might shed light on new therapeutic approaches for breast cancer." (PMID 32651974, 2021).
breast carcinoma (continued). "Therefore, we investigated whether ANKRD22 could regulate NuSAP1 expression by activating the Wnt/β-catenin signaling pathway in breast cancer." (PMID 32651974, 2021). "Therefore, we concluded that high expression of ANKRD22 could facilitate the progress of breast cancer, at least partially, by activating Wnt/β-catenin signaling via NuSAP1." (PMID 32651974, 2021). "Therefore, ANKRD22 might be a promising novel therapeutic target for the treatment of breast cancer." (PMID 32651974, 2021). "The inhibitory effects of ANKRD22 knockdown on the proliferation, invasion, and EMT of breast cancer cells were reversed by NuSAP1 overexpression." (PMID 32651974, 2021). "ANKRD22 knockdown suppressed the proliferation, invasion, and epithelial-mesenchymal transition (EMT) of breast cancer cells." (PMID 32651974, 2021). "ANKRD22 knockdown inhibited the proliferation, invasion, and epithelial-mesenchymal transition (EMT) of breast cancer cells, as confirmed by BrdU, colony formation, transwell, and immunoblot assays." (PMID 32651974, 2021). "Moreover, overexpression of NUSAP1 reversed the inhibitory effects of ANKRD22 knockdown on the proliferation, invasion, and EMT of breast cancer cells." (PMID 32651974, 2021). "A previous study indicated that ANKRD22 could serve as a transcription factor and activate the expression of E2F1 in lung cancer progression, which suggests that ANKRD22 might regulate other factors to affect breast cancer development and this needs further investigation." (PMID 32651974, 2021).
non-small cell lung carcinoma (6 papers, 2017 to 2024). A group of at least three distinct histological types of lung cancer, including non-small cell squamous cell carcinoma, adenocarcinoma, and large cell carcinoma. "The ANKRD22 is reported to promote non-small cell lung cancer, and STAMBPL1 is oncogenic in gastric cancer." (PMID 34178034, 2021). "In non-small cell lung cancer, ANKRD22 up-regulated the transcription of E2F1 and promoted the progression of cancer cells by enhancing cell proliferation." (PMID 34584137, 2021). "Ankyrin repeat domain-containing protein 22 (ANKRD22), a nucleus-encoded mitochondrial protein, is closely associated with the pathogenesis of multiple diseases, including prostate cancer, gastric mucosal injury, and non-small cell lung cancer and is highly expressed in activated macrophages." (PMID 38347610, 2024). "In addition, ANKRD22 promotes progression of non-small-cell lung cancer." (PMID 32260415, 2020). "In non-small cell lung cancer (NSCLC), ANKRD22 was upregulated in the tumor and correlated with relapse and overall survival." (PMID 31612115, 2019).
prostate carcinoma (6 papers, 2020 to 2025). A carcinoma that arises from epithelial cells of the prostate gland. "However, higher ANKRD22 expression levels in prostate cancer are associated with longer DFS following radical prostatectomy." (PMID 32260415, 2020). "In contrast, regarding prostate cancer, ANKRD22 is lowly expressed in the tumor group relative to the normal group, and the unfavorable correlation between ANKRD22 and the survival outcome of the patients was identified." (PMID 40225855, 2025).
Sepsis (3 papers, 2022 to 2025). Sepsis is defined as life-threatening organ dysfunction caused by a dysregulated host response to infection. "ANKRD22 is upregulated, encodes a specific mitochondrial protein, involved in progression of various cancers but connection to sepsis is unclear." (PMID 40927580, 2025). "Finally, ANKRD22, GPR84, GYG1, BLOC1S1, CARD11, NOG, and LRG1 were recognized as critical genes associated with sepsis molecular subtypes." (PMID 36035194, 2022). "In GSE154918 and GSE69063 datasets, ANKRD22, GPR84, GYG1, BLOC1S1, and LRG1 were all highly expressed in sepsis patients, whereas NOG and CARD11 were dramatically decreased in sepsis patients." (PMID 36035194, 2022). "There are remarkable differences in ANKRD22, GPR84, GYG1, BLOC1S1, CARD11, NOG, and LRG1 gene expression and enriched pathways among different molecular subgroups of sepsis, which may be the key factors leading to the heterogeneity of clinical symptoms and prognosis in patients with sepsis." (PMID 36035194, 2022).
gastric cancer (2 papers, 2020 to 2021). A primary or metastatic malignant neoplasm involving the stomach. "Although the expression of ANKRD22 was not significantly different between gastric cancer cells and the matched normal gastric epithelium, the expression of ANKRD22 was significantly elevated in CRC cells and pulmonary cancer cells compared with their normal epithelial counterparts." (PMID 31903135, 2020).
ovarian carcinoma (2 papers, 2020 to 2025). A malignant neoplasm originating from the surface ovarian epithelium. "This confers ANKRD22 a wide range of interactions with various proteins and might contribute to multiple disease-associated pathophysiological pathways, even cancer, such as lung, colorectal, and ovarian cancer; ANKRD22 functions in different roles, either as a tumor suppressor or supporter." (PMID 40225855, 2025).
Parkinson disease (2 papers, 2021 to 2023). A progressive degenerative disorder of the central nervous system characterized by loss of dopamine producing neurons in the substantia nigra and the presence of Lewy bodies in the substantia nigra and locus coeruleus. "Another study reported PLA2G6 (PARK14), an important paralog of ANKRD22, as a parkinsonism-associated gene, which its mutation influences the onset of neurodegenerative disorders, including early-onset parkinsonism." (PMID 34574038, 2021). "In a study of Parkinson's disease, ANKRD22 obtained through bioinformatics screening was shown to regulate neuronal development by regulating cell viability and IL-6 expression." (PMID 38102696, 2023).
cervical cancer (1 paper, 2020). A primary or metastatic malignant neoplasm involving the cervix. "Also, fluorescence colocalization analysis indicated that in colorectal, gastric, lung, and cervical cancer cells, almost all exogenous ANKRD22 was localized in mitochondria." (PMID 31903135, 2020).
chronic obstructive pulmonary disease (1 paper, 2025). A chronic and progressive lung disorder characterized by the loss of elasticity of the bronchial tree and the air sacs, destruction of the air sacs wall, thickening of the bronchial wall, and mucous accumulation in the bronchial tree. "After adjustment, elevated ANKRD22 and SERPING1 remained independent predictors, along with smoking, chronic obstructive pulmonary disease, cavitary disease, previous TB exposure, and treatment interruption." (PMID 41261705, 2025).
colon cancer (1 paper, 2025). "Specifically, CDC25C, ANKRD22, SEZ6L2, SERPINA1, and NOS2 were overexpressed in colon cancer tissues compared with normal tissues." (PMID 41425595, 2025).
gastritis (1 paper, 2024). Inflammation of the stomach. "In this study, the expression of ANKRD22 and USP15 were downregulated in viral meningitis groups, and ANKRD22 expression is similar to the one found in gastritis." (PMID 38347610, 2024).
invasive breast carcinoma (1 paper, 2022). A carcinoma that infiltrates the breast parenchyma. "We identify early processes and potential biomarkers, including CAMK2N1, MNX1, ADCY5, HOXC11 and ANKRD22, whose reduced expression is associated with the progression of DCIS to invasive breast cancer." (PMID 35697697, 2022).
metastatic carcinoma (1 paper, 2017). A carcinoma which has spread from the original site of growth to another anatomic site. "Successive up-regulation of ANKRD22 was observed in adjacent, primary and metastatic carcinoma tissues in the same NSCLC patient, and high expression levels of ANKRD22 were significantly related to relapse and short OS time in NSCLC patients." (PMID 28667340, 2017). "From the results, we identified ANKRD22 (ankyrin repeat domain 22) to be successively up-regulated in adjacent, primary and metastatic carcinoma tissues, and significantly affected tumor growth as a novel tumor-associated gene in NSCLC." (PMID 28667340, 2017).
tuberculosis (1 paper, 2025). A chronic, recurrent infection caused by the bacterium Mycobacterium tuberculosis. "This study evaluates serum ANKRD22 and SERPING1 as potential biomarkers of drug resistance through comparative analysis of expression profiles in drug-resistant versus drug-sensitive tuberculosis patients." (PMID 41261705, 2025). "The dual-marker approach involving ANKRD22 and SERPING1 shows promising clinical utility as a potential predictor of tuberculosis drug resistance, offering novel perspectives for improving diagnostic timelines and treatment strategies in drug-resistant TB management." (PMID 41261705, 2025).
viral meningitis (1 paper, 2024). Inflammation of the membranes surrounding the brain and spinal cord due to a viral infection. "In viral meningitis subjects, the ceRNA network was composed of hsa-miR-199b-5p, 4 mRNAs (ANKRD22, EVI2A, USP15, and C8orf88), and AC002511.1." (PMID 38347610, 2024). "CeRNA networks showed that ANKRD22 and USP15 were targets of hsa-miR-199b-5p and lncRNA AC002511.1 were co-expression with hisa-miR-199b-5p in viral meningitis patients." (PMID 38347610, 2024). "We speculated that the lncRNA AC002511.1 may act as a ceRNA to capture hsa-miR-199b-5p to regulate the expression of ANKRD22 and USP15 in the viral meningitis group." (PMID 38347610, 2024).